CEACAM1 (CEA cell adhesion molecule 1)
Diseases named in the same sentence as CEACAM1 in open-access papers (continued):
Sharing a sentence is not in itself a finding about the gene and the disease.
infection (continued). "Despite the use of two different in vitro experimental settings, different influenza virus strains, infection doses and time points, both studies agree that CEACAM1 plays an important role in influenza virus infection and warrants further investigation." (PMID 30341336, 2018). "Viral titers were significantly reduced in several organs by treatment with anti-CEACAM1 mAb 8 days after infection." (PMID 29967450, 2018). "The total number of CD8+ T cells, virus-specific Tet-GP33+ CD8+ T cell expansion, and intracellular cytokine (IFN-γ and TNF) production was limited in Ceacam1–/– mice 8 days after infection." (PMID 29967450, 2018). "On day 16 after infection, one group of mice was treated with an isotype control mAb, whereas a separate group of mice was treated with anti-CEACAM1 mAb." (PMID 29967450, 2018). "The cell adhesion molecule CEACAM1 has been shown to be critical for the regulation of immune responses during infection, inflammation and cancer." (PMID 30341336, 2018). "Analysis of expression kinetics of CEACAM1 showed that protein expression was visible as early as 6 hours post infection, peaking at 12 hours post infection." (PMID 27634893, 2016). "During systemic infection with cytopathic vesicular stomatitis virus, Ceacam1−/− mice can barely induce neutralizing antibody responses and die early after infection." (PMID 25692415, 2015). "While the human CEACAM1-expressing neutrophils can efficiently phagocytose Opa-expressing N. gonorrhoeae, the neutrophils showed little chemokine response to infection." (PMID 25188454, 2014). "Regarding colonization, the increase in CEACAM1 on epithelial cells upon bacterial challenge is likely to increase bacterial adherence and infection." (PMID 23941132, 2013). "Serum Nme-specific IgG was found to rise quickly in CEACAM1-humanized mice infected with 105 H44/76wt, even before the second intranasal infection." (PMID 23935487, 2013). "Again, the infection with these strains induced an elevated CEACAM1 expression (4.0-4.9 fold and 1.9-2.4 fold, respectively) comparable to their parental strains, indicating a CEACAM1-independent, more general mechanism for this effect." (PMID 23941132, 2013). "When PKCε was reconstituted by infection of the cells with recombinant adenovirus for 48 h, CEACAM1 expression was restored in PKCε−/− MEFs to levels over 30% of those in WT MEFs." (PMID 23469261, 2013). "Recently, we have shown that when CEACAM1 is genetically ablated in mice, neutrophils are over-produced and over-activated during infection with the model gram positive pathogen, Listeria monocytogenes, resulting in accelerated mortality." (PMID 22496641, 2012). "In vivo, MHV-A59 is strictly dependent on CEACAM1 for infection, but persistent infection of murine cells leads to the emergence of viruses with extended tropism." (PMID 22816037, 2012). "As expected, infection of CEACAM1-transfected cells with OpaCEA protein-expressing bacteria resulted in efficient internalization." (PMID 21298042, 2011). "CEACAM1 is a critical molecule well situated to play a communication role between epithelial cells, that represent the first barrier to infection, and immune cells that control infections that disrupt the epithelial barrier." (PMID 20404914, 2010). "In the case of Neisseria gonorrhoeae, neutrophils, due to their high levels of CEACAM1 expression, are a major target for spreading the infection in the urogenital tract." (PMID 20404914, 2010). "In contrast, upon infection with OpaCEA-expressing N. gonorrhoeae, 50 - 100 times more bacteria were recovered from cells expressing human CEACAM1." (PMID 20406467, 2010). "At day 6 after infection, the levels of virus-specific antibodies in Ceacam1−/− and WT mice were below the detection limit of the assay (data not shown)." (PMID 19621080, 2009). "Both at day 17 and 42 after infection, Ceacam1−/− mice showed a significantly higher spleen weight than WT mice." (PMID 19621080, 2009).
infection (continued). "In contrast, CEACAM1 expression was readily detectable in uninfected WT mice and was upregulated after infection, especially in bronchial epithelial cells." (PMID 19621080, 2009). "While we detected increased splenomegaly and a higher splenic latent viral load in Ceacam1−/− mice at day 17 after infection, a similar genomic load in the spleens of WT and Ceacam1−/− mice was detected at days 42 and 300 after infection." (PMID 19621080, 2009). "Similarly, the cytotoxic activity of activated CD8+ T cells and NK cells with high levels of CEACAM1 is also impeded during infection with the wild-type strain compared to ΔhopQ strain." (PMID 36891299, 2023). "CEACAM1 was shown to be essential for immune synapse formation in CD8+ T cells during infection." (PMID 34442377, 2021). "Furthermore, members of the CEACAM family are already upregulated upon infection by different influenza virus strains, as recently also shown for CEACAM1 and CEACAM5." (PMID 30973879, 2019). "However, 35 days after infection only a fraction of these virus-specific CD8+ T cells stained positive for CEACAM1." (PMID 29967450, 2018). "Similarly, the number of CD8+ T cells and the percentage of virus-specific Tet-GP33+ CD8+ T cells were reduced in peripheral organs and blood of Ceacam1–/– mice 8 days after infection with 200 PFU of LCMV-Docile." (PMID 29967450, 2018). "This suggests that CEACAM1-mediated anti-apoptotic events may be important for the resolution of influenza virus infection in vivo, which can be further investigated through infection studies with Ceacam1-knockout mice." (PMID 30341336, 2018). "Notably, in both isoforms we detected strong activation of spliceosome processing (more than 2-fold) of exon 7 containing mRNA transcripts between 12-24 h post infection (CEACAM1-4L, p < 0.001 and CEACAM1-3L, p < 0.01)." (PMID 24650050, 2014). "To test whether human CEACAM1 impacts systemic infection by Nme, we used an intraperitoneal challenge model." (PMID 23935487, 2013). "While meningococci could not be recovered from wild-type or CEABAC mice after the first day of infection, viable bacteria were recovered from CEACAM1-humanized mice for as long as seven days, with one transgenic animal still colonized at day ten." (PMID 23935487, 2013). "Notably, in vitro infection experiments revealed that PMNs derived from bone marrow of CEACAM1-humanized mice bound meningococci more effectively than did those taken from WT mice." (PMID 23935487, 2013). "This population was characterized for CEACAM1 expression, bacterial binding and infection." (PMID 23424672, 2013). "Global gene expression profiling of the host cells during infection with RSV or HPIV3 revealed increased transcription of carcinoembryonic antigen-related cell adhesion molecules (CEACAM1), CD47, fibronectin, interferon-stimulated genes and many other host cell adhesion molecules." (PMID 23742656, 2013). "We think that CEACAM1 fine-tunes the normal inflammatory response at the site of infection preventing hyper-inflammation, but in the case of Gram-negative pathogens that actually bind to neutrophils, inflammation is further blunted, favoring the infectious process." (PMID 22496641, 2012). "B cells which constitutively express CEACAM1 were most abundant in Ceacam1−/− mice after infection." (PMID 19621080, 2009). "The basis for this selection is not known, and the inability to detect CEACAMs on primary male urethral cells and the dissimilarities between human and murine CEACAM1 suggest Opa proteins may play other important roles during infection." (PMID 19956622, 2009). "Molecular identification of the CEACAM proteases, which can be of human or bacterium origin, may provide a clue to understand why the H. pylori HopQ–human CEACAM1/5 interaction undergoes transient reduction during infection of H. pylori carrying the functional T4SS." (PMID 35269634, 2022).
infection (continued). "We speculated that CEACAM1 could bind with TIM‐3 through the T lymphocyte surface, which may induce injury of immune function of lymphocytes at the late‐stage IS patients and finally result in increased risk of infection." (PMID 35657334, 2022). "Also, CEACAM1 might adopt a role different from its function(s) during bacterial colonization/infection and rather regulate the intestinal immune homeostasis and the inflammatory response, as we proposed based on our in vitro data." (PMID 31849868, 2019). "In addition, Ceacam1-knockout mice are available for further in vivo infection studies." (PMID 30341336, 2018). "We hypothesized that elevated production of IL-1β (2-3-fold over wild type) in response to infection was a major cause contributing to accelerated mortality and was likely attributable directly to neutrophils lacking the inhibitory co-receptor CEACAM1." (PMID 22496641, 2012). "Thus, pathogens that bind to CEACAM1 may interfere with its normal function, namely maintenance of communication between these two barriers to infection." (PMID 20404914, 2010). "In mice, FT671 treatment was well tolerated, reduced Ceacam1 expression, and protected against MHV-A59 infection." (PMID 41691482, 2026). "During infection, P5 functions as an adhesin that interacts with mucin, intracellular adhesion molecule 1 (ICAM-1), and carcinoembryonic antigen-related cell adhesion molecule 1 (CEACAM-1), promoting bacterial adherence to airway epithelial cells." (PMID 40977539, 2025). "In the future, attempts should be made to verify the interaction among CEACAM1, MMP‐9, and NGAL, and to further illustrate the roles of CEACAM1 in the IS, ischemia–reperfusion injury and secondary infection in the patients and animal models." (PMID 35657334, 2022). "We previously showed that HMPV-infected cells sense the infection via the RIG-I-dependent pathway, which results in CEACAM1 upregulation." (PMID 32698530, 2020). "Similarly, CEACAM1-deficient P14 CD8+ T cells exhibited limited IFN-γ production after in vitro restimulation with GP33 peptide, and this reduction in CD8+ T cell expansion and IFN-γ production was associated with enhanced viral titers in spleen, lung, liver, and serum at day 8 after infection." (PMID 29967450, 2018). "In the present study, we used a more physiologically relevant infection model, primary human ATII cells, to study the role of CEACAM1 in influenza virus infection, focusing on HPAI H5N1 virus." (PMID 30341336, 2018). "After infection with LCMV-Docile, LCMV-GP33-specific CD8+ T cells also expressed higher levels of CEACAM1." (PMID 29967450, 2018). "Following 24 hours of HMPV infection, significant elevation of viral loads was observed in cells expressing CEACAM1 Mut or GFP-ITIM, as compared to cells expressing the full length CEACAM1 gene." (PMID 27634893, 2016). "As can be seen, cells expressing shRNAs targeting CEACAM1 or SHP2, exhibited about a 3 fold increase in 35S-Methionine incorporation following infection, as compared to the scrambled shRNA." (PMID 27634893, 2016). "Combining the CEACAM1 colonization model with these transgenes and/or environmental insults such as viral co-infection, smoking or extremes in humidity may ultimately prove informative to understanding the transition from asymptomatic infection to disseminated disease." (PMID 23935487, 2013). "Based on the results obtained by functional analyses of CEACAM1 using purified immune cells one would expect an enhanced NK, T and B cell response in Ceacam1−/− mice, favoring the control of MHV-68 infection." (PMID 19621080, 2009). "At day 42 post infection, the numbers of B cells and CD4+ T cells were still higher in Ceacam1−/− mice than in WT mice, while the number of CD8+ T cells was nearly identical in both mouse strains." (PMID 19621080, 2009). "The pronounced increased expression of genes related to infection (CEACAM1 and DYSF) were not diminished." (PMID 38817614, 2024).
infection (continued). "The spleen-specific upregulation of CEACAM1 and ARG1 genes was observed after infection." (PMID 36835242, 2023). "Our results demonstrate that while mRNA levels of Ceacam1 remained unchanged among groups, those mice supplemented with vitamin D exhibited elevated expression of Ifnb1, Isg15, and Isg20 following MHV-3 infection." (PMID 38140675, 2023). "CEACAM1 was shown to be present as trans-dimer in solution, yet upon infection with H. pylori wild-type but not ΔhopQ mutant strain, the cross-linking efficiency of CEACAM1 is attenuated." (PMID 36891299, 2023). "In our studies, RV-A and RV-C infection induced CEACAM1 but blocking CEACAM did not inhibit M. catarrhalis binding to airway epithelial cells." (PMID 36733852, 2022). "Infection with RV-A and RV-C induced the expression of CEACAM1 by ~30-fold, while RV-B and M. catarrhalis did not have an effect on CEACAM1 expression." (PMID 36733852, 2022). "Furthermore, a disease that produces severe local inflammation accompanied by accumulation of CD11b cells at the site of infection, a VEGF-independent role of CEACAM1 has been characterized." (PMID 31039510, 2019). "Initially, we observed that a viable virus is required to induce CEACAM1 expression, since CEACAM1 was not induced following infection with UV-inactivated virus." (PMID 27634893, 2016). "Using this system, we observed the expression of IRF-1 but not IRF-2, a repressor of CEACAM1 transcription and other target genes, 12 h after infection with an apparent peak at 24 h." (PMID 24650050, 2014). "TNF-α and IL-1β were both upregulated during infection of normal CEACAM1-humanized but not significantly in WT mice." (PMID 23935487, 2013). "As a consequence, it has been suggested that JHM, in the absence of CEACAM1, uses an alternative, less effective and yet to be determined receptor in order to initiate infection." (PMID 22816037, 2012). "Surprisingly, infection of CEACAM1-transfected cells with Opa protein-negative meningococci resulted in bacterial internalization into the cells." (PMID 21298042, 2011). "To further confirm that full length murine CEACAM1-4S does not mediate bacterial internalization, we analysed transfected cells upon infection with fluorescein-labeled bacteria by an established flow cytometry method." (PMID 20406467, 2010). "In WT mice, lung epithelial cells indeed upregulated CEACAM1 early during infection, suggesting that the absence of CEACAM1 in Ceacam1−/− mice promotes NK cell activity while in WT mice, the strong expression of CEACAM1 downregulates NK cell activity." (PMID 19621080, 2009). "Similar to the spleen weight, the total number of spleen cells was significantly higher in Ceacam1−/− mice than in WT mice at day 17 (1.94 fold) and at day 42 (1.90 fold) after infection (data not shown)." (PMID 19621080, 2009). "Although derivatives of strain MS11 failed to induce apoptosis in HeLa cells, a similar efficient response as with N242 was observed with derivative N1163 (Opa57; PorBIA) upon infection of HeLa-CEACAM1 but not in HeLa-CEACAM3." (PMID 19300516, 2009). "In contrast, we did not detect viral reactivation in the lungs of Ceacam1−/− mice 42 days after infection." (PMID 19621080, 2009). "To further determine whether treatment with anti-CEACAM1 mAb acts specifically on CD8+ T cells, we transferred equal number of P14 × WT (CD45.1) splenocytes into Ceacam1–/– mice and then treated those mice with anti-CEACAM1 mAb or isotype mAb, followed by LCMV-Docile infection." (PMID 29967450, 2018). "After determining that infection with the OpaCEA-expressing N. gonorrhoeae N309 impaired MDDC maturation and decreased MDDC-induced T cell proliferation, we sought to determine if Opa-CEACAM1 interactions would also alter an epitope-specific T cell memory response." (PMID 23424672, 2013).
infection (continued). "Upon infection with Nme, a robust inflammatory response marked by elevated chemokines KC, MIP-1α and MIP-2 as well as cytokines TNF-α and IL-1β was observed in the nasal tissue of CEACAM1-humanized mice and also, to a significantly lower extent, in wild-type mice." (PMID 23935487, 2013). "Indeed, we found significant levels of Nme-specific IgA, but not IgG, in nasal lavage fluids of CEACAM1-humanized mice after twice being inoculated with 105 H44/76wt, but not in the other infection groups." (PMID 23935487, 2013). "Moreover, as a ligand of TIM‐3, CEACAM1 may involve in the negative immunoregulation of T lymphocytes, which may lead to severe immune dysfunction and subsequent infections." (PMID 35657334, 2022). "Infection of 293 cells with E. coli NadA or the E. coli control strain did not result in bacterial internalization and this was unchanged upon CEACAM1 expression, suggesting that the NadA receptor is not present in 293 cells and that CEACAM1 is not recognized by this bacterial invasin." (PMID 21298042, 2011).
adenocarcinoma (10 papers, 2006 to 2023). A common cancer characterized by the presence of malignant glandular cells. "We also found a significantly different expression of two very important plasma proteins related to lymphocyte functions: CD207, which showed a decreased plasma concentration, and CD66a/CEACAM1, which showed higher plasma levels in the adenocarcinoma group." (PMID 37610509, 2023). "To test, if Opa protein-negative meningococci are able to interact with CEACAM1 present on target tissues, we employed the adenocarcinoma cell line A549 derived from lung alveolar epithelium." (PMID 21298042, 2011). "Furthermore, CEACAM1, which is not expressed in the lung, has been identified in 2/3 of primary adenocarcinomas from this tissue and is considered a significant independent prognostic factor for survival." (PMID 16504122, 2006).
bacterial infection (8 papers, 2013 to 2025). "We also evaluated the molecular docking scores of UspA1 and CEACAM1 proteins against various drugs approved for treating bacterial diseases of humans, including COPD." (PMID 40019889, 2025). "CEACAM1 is a receptor on neutrophils, and CEACAM1 negatively regulates both NLRP3 inflammasome activation and immune response and has been found to increase the susceptibility of bacterial infection." (PMID 31093495, 2019). "NTHi375 adhesion assays were performed by using HeLa-BGP (biliary glycoprotein or CD66a, currently known as CEACAM1) cells, a HeLa derivative cell line stably expressing hCEACAM1-4L, and previously used to assess the impact of CEACAM1 on bacterial infections." (PMID 25894755, 2015). "On the other hand, it was shown that the presence of the ITIM of CEACAM1 was essential to suppress adaptive immune response upon bacterial infection of the genus Neisseria." (PMID 24858421, 2014). "Further, the data suggest a role for CEACAM1 and CEACAM5 in the phenomenon of increased host susceptibility to bacterial infection upon viral challenge in the human respiratory tract." (PMID 23941132, 2013). "Besides, in the human respiratory tract, CEACAM1 and CEACAM5 increase the host susceptibility to bacterial infection upon viral challenge." (PMID 34217339, 2021).
cardiovascular disease (4 papers, 2016 to 2025). "This mutual upregulation of TNF‐α and CEACAM1 would establish a vicious cycle promoting inflammaging and eventually the development of cardiovascular diseases." (PMID 39434463, 2025). "Notably, mRNAs for most genes associated with cardiovascular diseases (e.g., HSD3B2, PPARG, NLN and CEACAM1) were downregulated in the colons of HBP subjects." (PMID 36768972, 2023).